HIF1A (hypoxia inducible factor 1 subunit alpha)
Diseases named in the same sentence as HIF1A in open-access papers (continued):
Sharing a sentence is not in itself a finding about the gene and the disease.
melanoma (continued). "Additionally, miR-211 has been shown to function as a metabolic switch in melanoma cells by targeting the hypoxia inducible factor 1α (HIF-1α), and loss of miR-211–5p is expected to promote cancer hallmarks in human melanomas." (PMID 32050841, 2020). "In addition, as manipulation of the BRAF mutation was correlated in HIF-1α expression in vitro studies of melanoma cell lines and the thyroid cancer cell line (BCPAP), the link between BRAF mutation and Hif-1α expression is highly suspected." (PMID 32847004, 2020). "Depleted intra-tumoral ascorbic acid may thus play a role in the loss of HIF-1α regulation in melanoma." (PMID 26547841, 2015). "Furthermore, in hypoxic conditions, we evidentiated that ROS generated by mitochondrial mutations promote a proinvasive phenotype of melanoma cells though HIF-1α stabilization and growth factor secretion." (PMID 22272371, 2012). "Furthermore, we evidentiated that in hypoxic conditions these fibroblasts cause HIF-1α stabilization and promote a proinvasive phenotype of human melanoma cells through secretion of cytokines." (PMID 22272371, 2012). "Our study also suggests that advanced melanomas become glycolytic due to their hypoxic state, which might be linked to hypoxia-induced stabilization of HIF-1α activity." (PMID 23043612, 2012). "In a recent study we found a constitutive HIF-1α activity in malignant melanoma, which could be the cause of the observed CTGF overexpression." (PMID 21673687, 2011). "HIF-1α loss of function experiments were carried out in the WM9 metastatic melanoma cell line." (PMID 19919690, 2009). "Notably, a recent study with melanoma cells has shown for the first time that BRAF mutation increases HIF-1α expression." (PMID 18983642, 2008). "It is known that solid tumors, such as melanoma, are frequently characterized by an inadequate vasculature that is responsible for a transient or persistent oxygen deficiency promoting a metabolic adaptation of tumor cells to anaerobic glycolysis under the HIF-1α transcription factor activity." (PMID 36499700, 2022). "Furthermore, it has been found that the induction of melanogenesis in melanoma cells is associated with a dramatic increase in nuclear HIF1α expression accompanied by the upregulation of HIF1α-dependent genes involved in the regulation of glucose metabolism, angiogenesis and stress responses." (PMID 33730175, 2021). "However, the expression of HIF1-α in cancer cells is extensive, so it may be conducive to the expression of particular proteins associated with melanoma cell motility and invasion." (PMID 33352824, 2020). "Moreover, the intratumor production of the transcription factor AP-1 (c-Jun subunit) that regulates the expression of MMP-2 as well as the levels of HIF-1 (α subunit, HIF-1α), that are tightly linked to the aggressive phenotype of melanoma cells, were determined via Western blot." (PMID 32340166, 2020). "The high HIF-1α expression observed in melanomas might be linked to increased lactate production." (PMID 31781212, 2019). "In addition, endothelin-1 (ET-1)-dependent activation of the PI3K pathway could be directly linked to HIF1α stability under normoxic conditions in melanoma cells." (PMID 26000250, 2015). "Single-cell sequencing data of melanoma suggested that HIF-1α is a key gene regulating glucose metabolism and polarization in TAMs." (PMID 41988200, 2026). "The increase in HIF1A protein expression enables melanoma cells to acquire invasive features and drug resistance, leading to resistance of tumor cells to targeted therapeutic drugs such as BRAF V600E inhibitors." (PMID 41501031, 2026). "In melanoma, Elp3 modifies tRNA to affect the decoding of specific codons in HIF1A mRNA, thereby promoting the translation of HIF1A protein." (PMID 41501031, 2026).
melanoma (continued). "In vivo and in vitro experimental results demonstrated that HIF-1α upregulated glucose-serine metabolism in melanoma TAMs, thereby driving their polarization toward the M2 phenotype and consequently promoting tumor progression." (PMID 41988200, 2026). "In this study, we discovered that melanoma cells under mild hypoxia establish a pseudohypoxic state by raising ROS levels, thereby stabilizing HIF1α in an oxygen-independent manner." (PMID 40701956, 2025). "In contrast, miR-33a-3p and miR-33a act as oncosuppressors, binding to the 3′UTR of HIF-1α, suppressing its post-transcriptional expression, and inhibiting proliferation and glycolysis in melanoma cells." (PMID 40573249, 2025). "For this reason, this study aimed to compare the immunohistochemical expression of adipophilin, FASN, GLUT‐1, and HIF‐1α across three aggressive types of melanomas." (PMID 40867038, 2025). "To summarize, we have identified a mechanism responsible for mitochondria-mediated induction of pseudohypoxia that is essential for HIF1α stabilization and melanoma metastasis." (PMID 40701956, 2025). "Distribution of Adipophilin, FASN, and HIF‐1α expression levels in non‐metastatic melanomas, metastatic melanomas, and cutaneous nevi." (PMID 40867038, 2025). "In this study, we show that stabilization of HIF1α in metastasizing melanoma under mild hypoxia is regulated primarily by mitochondrial reactive oxygen species (ROS) rather than by reduced oxygen levels." (PMID 40701956, 2025). "HIF-1α intersects with multiple oncogenic signalling pathways relevant to melanoma progression, including PI3K–Akt–mTOR, RAS–RAF–MEK–ERK, Janus kinase (JAK)–STAT, Wnt–β-catenin, Notch, and NF-κB." (PMID 41463281, 2025). "TET2 downregulation and low levels of 5-hmC represent hallmarks for melanoma progression, while another marker of aggressive malignant phenotype in melanoma is represented by the accumulation of the Hypoxia-Inducible Factor-1a (HIF-1a)." (PMID 40427015, 2025). "It was demonstrated that HIF-1a silencing in a metastatic melanoma cell line led to a significant increase in the amount of TET2 enzyme, at both mRNA and protein levels." (PMID 40427015, 2025). "While our investigation sheds light on the role of the Hif1α-Hmox1 axis in melanoma-induced osteocyte ferroptosis, it focuses primarily on a subset of molecular pathways and regulatory mechanisms." (PMID 39814705, 2025). "We compared the expressions of EGFR, VEGFA, and HIF1A in a subset of patients that included the 30 patients with thyroid cancer and 32 patients with melanoma for whom expression data was available." (PMID 40869231, 2025). "In melanoma, angiogenesis is a key indicator of tumour proliferation rate, survival rate and metastasis to distant organs.HIF-1α is one of the initiating factors in the VM process." (PMID 41160271, 2025). "Melanoma cells generally exhibit high HIF-1α levels due to their epidermal location and limited oxygen availability." (PMID 39970778, 2025). "It has been shown that the reduction of HIF-1α expression in melanoma cells (for example by genetic silencing) leads to the decrease in the expression of hypoxic target genes and to the diminution of the stem-like characteristics of CSCs." (PMID 40806546, 2025). "In conclusion, while acknowledging the complexities surrounding Hif1α function in bone biology, our study provides new insights into its role in melanoma-induced osteocyte ferroptosis." (PMID 39814705, 2025). "Further, knockdown of Hif1α in MLO-Y4 cells reversed melanoma-derived CM-induced ferroptosis and apoptosis." (PMID 39814705, 2025). "This indicates that activation of HIF1α under conditions of mild hypoxia reduces CypD expression in melanoma cells and subsequently increases ROS levels, the factor essential for pseudohypoxic HIF1α stabilization." (PMID 40701956, 2025). "Similar observations were made using an overexpressing Hif1α model, with Hif1α overexpression further enhancing melanoma-derived CM-induced ferroptosis and apoptosis." (PMID 39814705, 2025).
melanoma (continued). "Acriflavine, a potent inhibitor of HIF-1α, has been studied for its ability to disturb glucose metabolism and suppress protective pathways in melanoma cells, even under normoxic conditions." (PMID 40867277, 2025). "In melanoma, HIF-1α can stimulate the expression of the melanocyte-specific transcription factor MITF (microphthalmia-associated transcription factor) even in hypoxia, which paradoxically favors tumor growth." (PMID 40806546, 2025). "This study demonstrates that silencing KLF4, SHH, and HIF1α in melanoma CSCs leads to coordinated changes in cytoskeletal structure, molecular composition, and cell morphology, reflecting a loss of stem-like properties." (PMID 40854961, 2025). "In this study, we aimed to investigate how silencing of the KLF4, SHH, and HIF1α genes affects the cytoskeletal structure and biochemical characteristics of melanoma CSCs." (PMID 40854961, 2025). "Calpain‐mediated filamin A cleavage has been reported to control HIF1α activity in several cancer cell lines, including melanoma, osteosarcoma, and cervical cancer cells." (PMID 40151834, 2025). "It was previously reported that the acquired resistance to rhARG1 in melanoma cells in vivo was due to the altered expression of the two transcription factors c-Myc and HIF-1α, which are positive and negative regulators, respectively, of ASS1 gene expression." (PMID 40563540, 2025). "Hif1α overexpression significantly increased Hmox1 expression in untreated cells, and after treatment with melanoma-derived CM." (PMID 39814705, 2025). "The integration of molecular, spectroscopic, and imaging data provides a comprehensive perspective on how silencing of KLF4, SHH, and HIF1α affects melanoma CSCs." (PMID 40854961, 2025). "Inhibition of the MCU reduced accumulation of mitochondrial calcium, decreased oxygen consumption and ROS production, and induced degradation of HIF1α in CypD KO melanoma cells." (PMID 40701956, 2025). "Confocal staining and western blot of Hif1α in MLO-Y4 stimulated with melanoma CM showed an up-regulation of Hif1α after treatment with melanoma-derived CM." (PMID 39814705, 2025). "We decided to use cobalt(II) chloride for hypoxia induction in melanoma cells to investigate, firstly, the impact of the increased HIF-1α on the phototoxicity of PSs." (PMID 40867888, 2025). "Immunofluorescence of Hif1α confirmed its upregulation in the Roxadustat group compared to the melanoma group." (PMID 39814705, 2025). "In melanomas, positivity for HIF‐1α was observed in less than 50% of metastatic and non‐metastatic cases, and almost all of them were in focal patterns." (PMID 40867038, 2025). "In the context of melanoma-induced osteocyte ferroptosis, our findings suggest that the Hif1α/Hmox1 axis plays a crucial role." (PMID 39814705, 2025). "The influence of HIF-1α stabilization on the effectiveness of anti-tumor CD8 T cells was further affirmed using the TiRP-derived T429.11 melanoma mouse model, which expresses the P1A antigen and exhibits a partial response to the ACT of TCRP1A CD8 T cells." (PMID 39242595, 2024). "Here, we demonstrate that TIPE facilitates the Warberg effect by promoting dimeric PKM2-mediated HIF-1α transactivation in melanoma." (PMID 39728923, 2024). "This study demonstrates compelling evidence for a link between NLGN4X-controlled neuronal differentiation and its ability to control HIF1A signalling in melanoma." (PMID 38902533, 2024). "It has also been reported that HIF-1α can affect the regulation of tumor chemokines by miRNA in the B16-F10 melanoma mouse tumor model." (PMID 38771435, 2024). "First, to monitor tumor cell adaptation to long term and severe hypoxia, we established a reporter cell line using a lentiviral HIF1α-eGFP fusion construct in B16-F10 mouse melanoma cells." (PMID 38977895, 2024). "In line, loss of VBP1, a member of the prefoldin complex, has been shown to trigger HIF1A accumulation in B16F10 mouse melanoma cells and in zebrafish." (PMID 38902533, 2024).
melanoma (continued). "While these roles are well established, recent studies continue to update the importance of HIF-1α in melanoma immunity and metastasis." (PMID 38426087, 2024). "Accordingly, our recent study found that deletion of HIF1α reduces the B16 melanoma tumor growth and expands the population of effector memory function of CD8+ T cells." (PMID 38361941, 2024). "H1 receptor antagonists reduced tumor growth, mast cell infiltration, and VEGF levels through the inhibition of hypoxia-inducible factor-1alpha (HIF-1α) in melanoma-bearing mice." (PMID 38482531, 2024). "The tumor vasculature in melanoma is hypoxic in comparison to the oxygen pressure in other organs, thus, the expression of HIF-1-α is stabilized." (PMID 38338464, 2024). "Taken together, HIF-1α plays key roles in regulating melanoma signaling responsible for EMT, and ultimately metastasis, and immune responses." (PMID 38426087, 2024). "Preclinically, the inhibition of HIF1a by EZN‐2968 enhanced the therapeutic efficacy of PD‐1 blockade in the treatment of both melanoma and TNBC by reducing the infiltration of ALCAMhigh macrophages and exhausted CD8+ T cells and promoting anti‐tumor immunity." (PMID 38956900, 2024). "In summary, this study demonstrates that the molecular mechanism of celastrol in the treatment of B16-F10 melanoma cells involves the inhibition of HIF-1α mRNA expression by regulating the PI3K/AKT/mTOR signaling pathway." (PMID 38771435, 2024). "TIPE-mediated PKM2 dimerization consequently promoted HIF-1α activation and glycolysis, which contributed to melanoma progression and increased its stemness features." (PMID 39728923, 2024). "In melanoma, targeting HIF-1α has been reported to drive cytotoxic immune effector cells into the tumor and improve combination immunotherapy." (PMID 38364250, 2024). "For example, the tRNA U34 enzyme genes promoted glycolysis in melanoma cells by regulating the translation of HIF-1α mRNA." (PMID 39695074, 2024). "The alteration of HIF-1a expression level in anoxic microenvironment decreased the expression of melanocyte marker and increased its invasiveness in melanoma cells." (PMID 38364250, 2024). "The newly identified TIPE/PKM2/HIF-1α axis is an ideal therapeutic target for melanoma and opens an avenue for the development of a novel strategy for precision therapy." (PMID 39728923, 2024). "TIPE binds to PKM2, inducing its dimeric transformation by enhancing ERK-dependent PKM2 Ser37 phosphorylation, and thus activating the transcription of HIF-1α, providing tumorigenicity and cancer stem-like phenomena for melanoma progression." (PMID 39728923, 2024). "The NLGN4X-dependent activation of HIF1A was essential for melanoma cell migration and invasion and, re-expression of NLGN4X in metastatic melanoma reduced tumour growth in human skin organoids." (PMID 38902533, 2024). "have shown that hypoxia promotes calpain-induced filamin-A proteolysis in melanoma cells, which in turn facilitates HIF-1α nuclear translocation." (PMID 39156707, 2024). "These include increased expression of CSPG4 and CHST15 in melanoma cells, as well as increased expression of versican in prostate epithelial cells, of Wnt9A in colonic epithelial cells, and of HIF-1α in bronchial and colonic epithelial cells." (PMID 38892038, 2024). "The endothelin axis modulates the TME via HIF-1α in two known cases: ET1 has been shown to stabilize HIF-1α by inhibiting PHD2 in melanoma and lymphoid ECs, mimicking and enhancing hypoxia in the TME." (PMID 38785410, 2024). "Several studies establish a clear relationship between some miRNAs and the HIF-1α signalling pathway in melanoma." (PMID 39594467, 2024). "Because HIF-1α is upregulated in melanoma and contributes to the malignant transformation of melanocytes, we sought to identify a novel epigenetic modulator of HIF-1α, thereby providing a therapeutic target in melanoma." (PMID 36831463, 2023).
melanoma (continued). "In this study, we delineated an epigenetic mechanism in which the epigenetic eraser HDAC8 stabilizes HIF-1α expression and promotes melanoma progression." (PMID 36831463, 2023). "For example, in the case of melanoma cells, melanomas exosomes produce HIF-1α and HIF-2α in M1 and M2 macrophages, respectively." (PMID 38139779, 2023). "In another study, PI3K/AKT and HIF-1α activated Notch1 signaling under hypoxia during melanoma development." (PMID 36901857, 2023). "Consistent with previous findings, FK228, a potent HDAC1 and HDAC2 inhibitor, significantly reduced the HIF-1α protein levels in melanoma." (PMID 36831463, 2023). "Through inhibitor screening, we identified that HDAC8 effectively regulates HIF-1α in melanoma cells." (PMID 36831463, 2023). "Collectively, these findings reveal HDAC8 as a novel epigenetic modulator of HIF-1α and present a novel therapeutic strategy in treating patients with melanoma." (PMID 36831463, 2023). "To this end, we injected syngeneic B16F10 melanoma cells intravenously into HIF‐1α KO mice as well as the corresponding WT littermates and analyzed the number of pulmonary metastases 2‐week postinjection." (PMID 36987917, 2023). "Hypoxia-inducible factor-1 α (HIF-1α) is overexpressed in melanoma and plays a crucial role in driving malignant transformation in cancer cells." (PMID 36831463, 2023). "In BRAF V600E-positive melanocytes and melanoma cells, the HIF-1α and VEGF levels were elevated, possibly due to the downregulation of VHL expression by BRAF mutations." (PMID 36901857, 2023). "After revealing the crucial role of HDAC8 in regulating HIF-1α along with its tumorigenic function in melanoma in vitro, we analyzed the significance of HDAC8 expression in melanoma patient survival." (PMID 36831463, 2023). "In this study, we show that HDAC8 is an epigenetic regulator of HIF-1α, a critical transcription factor that drives tumor progression in various cancers, including melanoma." (PMID 36831463, 2023). "Compared to primary melanoma, the expression levels of HIF1A and HDAC8 were significantly elevated in metastatic melanoma." (PMID 36831463, 2023). "Here, we evaluated the effects of several HDACis and found that PCI-34051 most effectively suppresses HIF-1α expression in melanoma." (PMID 36831463, 2023). "Its best-known function with respect to cancer is to inhibit the expression of HIF1-α through the regulation of ROS to inhibit melanoma cell growth." (PMID 37761814, 2023). "T For instance, the lncRNA, LINC00518, induces radiation resistance in melanomas by regulating HIF-1α expression and modulating glycolysis." (PMID 37008055, 2023). "Collectively, the patient survival analysis supports our findings that HDAC8 enhances the expression of HIF-1α and promotes tumor progression in melanoma." (PMID 36831463, 2023). "Similar to the PCI-34051 results, the genetic ablation of HDAC8 greatly reduced HIF-1α levels under both normoxic and hypoxic conditions in melanoma cells." (PMID 36831463, 2023). "For example, HIF-1a in hypoxic melanoma cells induced translocation and secretion of IL-10, which induced macrophage activation to the alternative M2 phenotype." (PMID 36816959, 2023). "Remarkably, in human melanoma cell lines, the expression of PD-L1 was differentially affected by hypoxia, and the role of HIF-1α was less important compared to the IFN-γ/JAK/STAT pathway stimulated by IFN-γ." (PMID 37834467, 2023). "The BRAF V600E mutation, at least in part, induces angiogenesis through HIF-1α/VEGF, and the treatment of SK-MEL-28 melanoma cells with the BRAF inhibitor PLX4720 reduces VEGF expression and secretion." (PMID 36901857, 2023). "Treatment of melanoma mice with H1-receptor antagonist blocks HIF-1α expression and suppresses tumor growth and mast cells infiltration, suggesting that mast cell-derived HIF-1α accelerates melanoma growth." (PMID 36761171, 2022).